HDAC6 (histone deacetylase 6)
Diseases named in the same sentence as HDAC6 in open-access papers (continued):
Sharing a sentence is not in itself a finding about the gene and the disease.
cervical cancer (continued). "In conclusion, isoflurane enhances proliferation of cervical cancer cells mediated by the activation of HDAC6 via mTOR pathway." (PMID 32833118, 2021). "Knockdown of HDAC6 was demonstrated to hinder proliferation of cervical cancer HeLa cells, indicating that HDAC6 plays a key role in the carcinogenesis of cervical cancer." (PMID 32833118, 2021). "HDAC1 and HDAC6 are overexpressed in cervical cancer and contributes in cancer progression, metastasis and angiogenesis." (PMID 31766427, 2019). "For example, active participation of histone deacetylases (HDAC1, HDAC5 and HDAC6) in cervical cancer and significant degree made them vital for network maintenance." (PMID 31766427, 2019). "We found an inverse correlation of miR-22 and HDAC6 expression in cervical cancer cells and tissue samples." (PMID 30379969, 2018). "HDAC8 shows functional redundancy with HDAC6 when overexpressed in cervical cancer cells, HeLa, and deacetylaes ac-lys40 of alpha tubulin leading to cervical cancer proliferation and progression." (PMID 29716651, 2018). "MiR-22 acts as tumor suppressor by inhibiting proliferation and migration, and by inducing apoptosis of cervical cancer cell lines by targeting the 3’UTR of HDAC6." (PMID 30379969, 2018). "In the present study, we determined the expression levels of miR-22 and its downstream target, HDAC6, in cervical cancer cells and tissue samples." (PMID 30379969, 2018). "In our study, we found that inhibition of METTL3 could significantly restore ciliation in cervical cancer cells, which was characterized by increased elongation of cilia length via inhibiting HDAC6 expression." (PMID 39535388, 2025). "Since m6A modification is crucial for regulating HDAC6 expression, we wonder whether targeted demethylation of HDAC6 mRNA by dm6ACRISPR can inhibit the tumorigenesis of cervical cancer cells." (PMID 39535388, 2025). "We found that in the viral carcinogenesis pathway, E7 directly acts on HDAC6 to induce cell transformation in HPV infection-related cancers (cervical cancer, anal cancer, penile cancer, and head and neck carcinoma), inducing the malignant transformation of cells." (PMID 39411320, 2024). "Our results indicate that alteration in HDAC6 and DNMT3B expression is associated with high-risk human papillomavirus infection and could promote the occurrence and development of cervical cancer." (PMID 39411320, 2024). "Low expression of miR-199a could block the inhibitory effect of HDAC6 silencing on the development of cervical cancer cells in vivo and in vitro." (PMID 37397007, 2023). "The levels of Orai1, STIM1, and HDAC6 were upregulated in cervical cancer cells." (PMID 36230965, 2022). "Thus, the microtubule-associated HDAC6 can be a cancer-specific target of malignant phenotypes mediated by STIM1-dependent SOCE, at least for cervical cancers with upregulation of HDAC6 and STIM1." (PMID 35008759, 2021). "In conclusion, Isoflurane enhanced proliferation of cervical cancer cells through upregulation of histone deacetylase 6, which was associated with mTOR-dependent pathway, but not AKT-mediated pathway." (PMID 32833118, 2021). "Our findings indicate that activation of mTOR pathway might be an explanation for the isoflurane-induced expression of HDAC6 in cervical cancer cells." (PMID 32833118, 2021). "Increased HDAC6 expression was consistent with cervical lesion progression, indicating that HDAC6 might play an important role in cervical cancer progression." (PMID 30379969, 2018). "This is the first report that HDAC6 is regulated by miRNA in cervical cancer." (PMID 30379969, 2018).
cervical cancer (continued). "Similarly, we also found that expression of HDAC6 was higher in all of four cervical cancer cell lines than in an immortalized human cervical keratinocyte line (HCK1T)." (PMID 30379969, 2018). "This study is one step forward in understanding miR-22-dependent regulation, provides an insight into the interaction network of viral oncogenes, miR-22 and HDAC6, and might indicate a target in application for therapy of cervical cancer in the future." (PMID 30379969, 2018). "In addition, HDAC6 expression levels were significantly decreased in both HeLa and SiHa cells overexpressing m6A demethylase ALKBH5, suggesting that HDAC6 expression in cervical cancer cells is closely associated with m6A modification." (PMID 39535388, 2025). "Interestingly, the expression of STIM1 and Orai1 was increased in most cervical cancer specimens, while the acetylation of tubulin was decreased, suggesting that specific targeting of HDAC6 in cervical cancer can inhibit STIM1-Orai1-mediated cervical neogenesis." (PMID 36230965, 2022). "However, whether HDAC6 is involved in the isoflurane-induced proliferation of cervical cancer cells and the related mechanisms are yet to be elucidated." (PMID 32833118, 2021). "Through cross-screening of HPV infection-related DEGs and cervical cancer-related DEGs, we identified five significantly upregulated DEGs, e.g., GP6, CD36, HDAC6, ESPL1, and DNMT3B." (PMID 39411320, 2024). "To further investigate the regulatory effect of the E7 gene on HDAC6 and DNMT3B in HPV-negative cervical cancer cells, we infected C33A cells with recombinant viruses expressing the E7 gene (Ad4-HPV16E7, Ad4-HPV16E6E7, Ad4-HPV18E7, and Ad4-HPV18E6E7)." (PMID 39411320, 2024). "To further analyze the regulatory effect of the E6/E7 genes on HDAC6, we searched the Kyoto Encyclopedia of Genes and Genomes (KEGG) database for pathways related to HPV infection in cervical cancer." (PMID 39411320, 2024). "HDAC6 and wingless-related integration site 5a (Wnt5a) are highly expressed in human papillomavirus (HR-HPV)-positive cervical cancer tissues." (PMID 36076996, 2022). "HDAC6 promoted the proliferation and inhibited the apoptosis of HPV-infected cervical carcinoma cells by decreasing the expression of miR-199a, an inhibitor of wnt signaling." (PMID 36076996, 2022). "As a result, in line with the oncogenic role of the METTL3/HDAC6 axis, higher expression of both METTL3, YTHDF3, and HDAC6 was observed in tumor tissues when compared to the matched adjacent normal tissues from cervical cancer patients." (PMID 39535388, 2025). "In addition, survival analysis showed that cervical cancer patients with increased expression of METTL3, YTHDF3, and HDAC6 represented an obviously unsatisfied overall survival (OS)." (PMID 39535388, 2025). "The upregulation of HDAC6 induced by METTL3 over‐expression is capable of inhibiting cilia elongation and acetylation of α‐tubulin, thereby shortening cilia length and accelerating the progression of cervical cancer both in vitro and in vivo." (PMID 39535388, 2025). "Although the oncogenic role of HDAC6 has been reported in cervical cancer, its mechanism in the development of HPV-positive cervical cancer remains unclear." (PMID 39411320, 2024).
cervical cancer (continued). "Furthermore, the recombinant viruses expressing HPV16/18 E7 can upregulate the HDAC6 and DNMT3B genes involved in cervical cancer pathways, thereby influencing the cell cycle." (PMID 39411320, 2024). "Results suggest that AKT seems not the direct upper stream factor of HDAC6 in isoflurane-induced proliferation of cervical cancer cells." (PMID 32833118, 2021). "In cervical cancer cells, but not in noncancerous epithelial cells, hyperacetylation of α-tubulin by pharmacological blockade or silencing of HDAC6 abrogated microtubule-dependent STIM1 translocation and inhibit SOCE activation." (PMID 31252656, 2019). "Although HDAC6 is a proven tubulin deacetylase and HDAC6 inhibition results in cancer cell death, its expression is not altered in cervical cancer as evident by the mRNA, protein expression and enzyme activity studies." (PMID 29716651, 2018). "It was found that the microtubule-dependent STIM1 translocation and subsequent SOCE activation of cervical cancer cells, but not in non-cancerous epithelial cells, was abrogated upon hyperacetylation of α-tubulin by pharmacological blockade or silencing of HDAC6." (PMID 35008759, 2021).
ciliopathies (16 papers, 2012 to 2025). "Dysregulation of HDAC6 activity is implicated in ciliopathies, a group of disorders characterized by defective ciliary structure or function, resulting in widespread organ involvement and significant morbidity." (PMID 40167251, 2025). "In conclusion, both cilia‐targeted therapies and HDAC6 inhibitors represent promising avenues for treating ciliopathies." (PMID 40167251, 2025). "In doing so, this review sets the stage for future investigations into HDAC6‐targeted therapies, potentially transforming the clinical management of ciliopathies and significantly improving patient outcomes." (PMID 40167251, 2025). "In this review, we will explore the intricate relationship between HDAC6 and cilia and discuss the promising therapeutic potential of the HDAC6‐ciliary axis as a target for the treatment of ciliopathies." (PMID 40167251, 2025). "Aberrant expression or activity of HDAC6 can disrupt these pathways, leading to the development of ciliopathies, a group of genetic disorders characterized by defective ciliary function." (PMID 40167251, 2025). "HDAC6 inhibitors hold promise beyond virology, with roles in inflammation, oncology, and ciliopathies." (PMID 41135681, 2025). "This review provides a comprehensive examination of the molecular dynamics of HDAC6 in the context of ciliogenesis and ciliopathies, emphasizing its dual role in the deacetylation of microtubules and regulation of the ciliary axoneme." (PMID 40167251, 2025). "HDAC6 inhibitors show promise in restoring ciliary function, offering new treatment avenues for ciliopathies." (PMID 40167251, 2025). "Collectively, it is proposed that the miR‐669a‐5p/G3BP/HDAC6/AKAP12 axis is a promising pharmaceutical target for treating ciliopathies." (PMID 38088586, 2024). "OIR mice were treated with an intravitreal injection of tubastatin A, a selective inhibitor for HDAC6, which has been shown to restore cilium assembly in multiple cell lines and organs and used as an investigative treatment for various ciliopathies." (PMID 35619548, 2022). "We intend to expand this approach toward developing a precision pharmacology strategy to selectively deliver HDAC6 inhibitors to the base of primary cilia for the treatment of ciliopathies including chronic polycystic kidney diseases." (PMID 34250905, 2021). "By deacetylating α‐tubulin, HDAC6 acts as a key driver of primary cilium disassembly and has already been proposed as a possible therapeutic target for ciliopathies." (PMID 32383329, 2020). "Dysregulation of HDAC6 contributes to ciliopathies, affecting multiple organs." (PMID 40167251, 2025). "HDAC6‐targeted therapies, in particular, offer broad clinical prospects for treating ciliopathies." (PMID 40167251, 2025). "However, while the involvement of HDAC6 in cilia formation and function is well documented, the specific mechanisms by which it influences cilia‐mediated signaling in different ciliopathies remain incompletely understood." (PMID 40167251, 2025). "Additionally, combining HDAC6 inhibitors with other therapeutic approaches could enhance treatment outcomes, particularly in complex ciliopathies where multiple pathways may be involved." (PMID 40167251, 2025). "Similarly, its role in regulating primary cilia disassembly may envisage HDAC6 as a molecular target for the treatment of ciliopathies, a family of diseases presenting both genotypic and phenotypic heterogeneity, primarily affecting the CNS." (PMID 39595195, 2024). "Collectively, these results elucidate a previously unidentified miR‐669a‐5p/G3BP/HDAC6/AKAP12 signaling pathway that regulates cilium length, providing potential pharmaceutical targets for treating ciliopathies." (PMID 38088586, 2024). "Our findings confirm that ciliopathies can result from an excess of PIP2 and indicate that ciliopathies could be ameliorated by AurkA and HDAC6 inhibitors." (PMID 35079141, 2022).
ciliopathies (continued). "In summary, butyrate targets cancer cell growth and migration and enhances the anti-cancer effects of HDAC6 inhibitors in CCA cells, suggesting that butyrate may have therapeutic effects in CCA and other ciliopathies." (PMID 35096835, 2021).
leukemia (16 papers, 2008 to 2026). A malignant (clonal) hematologic disorder, involving hematopoietic stem cells and characterized by the presence of primitive or atypical myeloid or lymphoid cells in the bone marrow and the blood. "Finally, HDAC6 silencing impaired leukemia outgrowth in mice, associated with reduction of Notch3 full-length protein in vivo." (PMID 29643474, 2018). "In leukemia cells, HDAC6 inhibitors can inhibit the process of α-tubulin deacetylation by HDAC6, disrupting the microtubule dynamics system and ultimately inhibiting cancer cell migration." (PMID 36457493, 2022). "The targeting of HDAC6 appears promising because it is overexpressed in many types of cancers, including certain leukemia subtypes." (PMID 32013157, 2020). "In leukemia cells, a significant amount of nuclear HDAC6 was revealed, considering the interaction between the nuclear localization sequence (NLS) of HDAC6 and importin-α, which translocates HDAC6 into the nucleus." (PMID 32013157, 2020). "While its prognostic significance remains debated, we demonstrate that HDAC6 loss significantly impairs myeloid leukemia progression in vivo, despite having no functional impact on leukemia cell proliferation in vitro." (PMID 41794832, 2026). "The HDAC6-based effects on Hsp90 seem to be important in leukemia cells." (PMID 34959719, 2021). "The specific nuclear localization of HDAC6 in leukemia cells might offer a therapeutic advantage to specifically target those cells." (PMID 32013157, 2020). "Overall, these results show that inhibition of HDAC6 activity exerts anti-leukemia effects in mice." (PMID 29643474, 2018). "In human leukemia K562 cells, the HDAC6 inhibitor disrupts the antiapoptotic pathway of Akt." (PMID 29515768, 2018). "Consequently, the presence of HDAC6 in the nucleus of leukemia cells could be explained by red levels of acetylation within the NLS region, compared to other cell types." (PMID 32013157, 2020). "Thus, HDAC6 silencing by specific shRNA was very recently also demonstrated to impair leukemia outgrowth in xenografted mice associated with increased Notch3 accumulation in lysosomes and elevated apoptosis of T-cell acute lymphoblastic leukemia cells." (PMID 30544838, 2018). "The same experiment performed using the leukemia cell line MV4-11 validated HDAC1 (Kdapp = 16 μM), HDAC2 (Kdapp = 14 μM), and HDAC6 (Kdapp = 21 μM) and identified HDAC3 (Kdapp = 13 μM) and HDAC10 (Kdapp = 5 μM) as additional targets of (R/S)-LM." (PMID 37322067, 2023). "Hence, a strong inhibition of HDAC6 by SF5-SAHA can contribute to its anticancer properties, in particular, in the HCC and leukemia cells where SF5-SAHA was more antiproliferative than SAHA." (PMID 34959719, 2021). "HDAC6 is a class IIB histon deacetylase and identified as target of anti-leukemia therapy." (PMID 19761576, 2009).
endothelial dysfunction (14 papers, 2020 to 2025). In vascular diseases, endothelial dysfunction is a systemic pathological state of the endothelium (the inner lining of blood vessels) and can be broadly defined as an imbalance between vasodilating and vasoconstricting substances produced by (or acting on) the endothelium. "Activation of Rho GTPases and HDAC6 appear to act in coordinated manner to cause MT-driven endothelial dysfunction." (PMID 34777018, 2021). "In this study, we extend our previous findings of HDAC6 to establish its contribution to the endothelial dysfunction that underlies development of atherosclerosis in vivo." (PMID 34220539, 2021). "Histone deacetylase 6 inhibition may protect against erectile and endothelial dysfunction associated with hypercholesterolemia." (PMID 39790566, 2024). "Previous studies showed that HDAC6 knockdown or TubA can protect the TNF‐induced endothelial dysfunction." (PMID 37665135, 2024). "The aim of the current study is to investigate the potential role of tubacin, a histone deacetylase 6 (HDAC6) inhibitor, in restoring erectile function in a hypercholesterolemia-induced endothelial dysfunction model." (PMID 39790566, 2024). "Increased activity of HDAC6 has shown to increase lipid-induced endothelial dysfunction in vitro as well as decrease CSE expression in aortic endothelial cells." (PMID 39790566, 2024). "This suggests that inhibition of HDAC6 via tubacin administration can provide a protective effect against endothelial dysfunction induced by a hypercholesteremic environment." (PMID 39790566, 2024). "It indicates that HDAC-mediated epigenetic programming also involves other beneficial mechanisms to combat against endothelial dysfunction beyond HDAC6-mediated control of MT dynamics that needs future attention." (PMID 34777018, 2021). "We showed previously that increased HDAC6 activity is a major culprit in OxLDL-induced endothelial dysfunction in vitro." (PMID 34220539, 2021). "In this context, our results indicating an enhanced HDAC6 protein expression by AngII further suggested that an increase in ROS plays a role in endothelial dysfunction and hypertension." (PMID 32755037, 2020). "In this study, we demonstrated that HNK contributes to ameliorate AngII‐induced hypertension and endothelial dysfunction by regulating the HDAC6‐mediated CSE degradation that is dependent on CSE K73 acetylation and ubiquitination." (PMID 32755037, 2020). "As an example, honokiol, a natural compound from magnolia plants, was very recently shown to ameliorate Angiotensin II-induced hypertension and endothelial dysfunction via inhibition of histone deacetylase 6 (HDAC6)." (PMID 33374186, 2020). "In ox-LDL-treated HAECs and aortas from ApoE–/– mice, HDAC6 was upregulated, and its selective inhibitor tubacin prevented endothelial dysfunction and the development of AS." (PMID 33282862, 2020). "Furthermore, tubacin, a tubulin acetylation inducer that inhibits histone deacetylase 6 (HDAC6), was found to mitigate endothelial dysfunction by upregulating the expression of eNOS." (PMID 39769167, 2024). "Likewise, increasing evidence has supported our study results that HDAC6 plays a decisive role in endothelial dysfunction, oxidative stress, and inflammation and has a protective role in promoting vascular homeostasis." (PMID 38001953, 2023). "Whether AMPK signaling pathway is involved in DRD1-mediated protection against mechanical stretch-induced endothelial dysfunction through mutual regulation with HDAC6 merits further investigation." (PMID 33456556, 2021). "As therapeutic potential of HDAC6 inhibition has been evaluated in cardiovascular, neurodegenerative diseases and cancers, recent studies have assessed the role of HDAC6 inhibition in endothelial dysfunction-derived ALI." (PMID 34777018, 2021).